CD70 (CD70 molecule)
Description:
Expressed at the plasma membrane of B cells, it is the ligand of the CD27 receptor which is specifically expressed at the surface of T cells. The CD70-CD27 signaling pathway mediates antigen-specific T cell activation and expansion which in turn provides immune surveillance of B cells.
Synonyms: CD27-L; CD27L; CD27LG; TNFSF7; LPFS3; TNLG8A
Tractability: Antibody: a drug acting on it is in phase 2 or 3 trials; UniProt places it where antibodies can reach, with high confidence; its Gene Ontology location is reachable by antibodies, with high confidence; UniProt predicts a signal peptide or a membrane-spanning region. PROTAC: ubiquitination databases record sites on it; its protein half-life has been measured. Other modalities: a drug acting on it is in phase 2 or 3 trials.
Target class: Surface antigen
Gene: Protein-coding gene on chromosome 19 (6,583,183 to 6,604,103, reverse strand). Ensembl gene ENSG00000125726.
Subcellular location: Cell membrane
Subcellular location (Human Protein Atlas): Nucleoplasm
Pathways (Reactome):
Immune System: TNFs bind their physiological receptors
Gene Ontology:
Molecular function: protein binding; receptor ligand activity; tumor necrosis factor receptor binding
Biological process: adaptive immune memory response involving T cells and B cells; B cell mediated immunity; B cell proliferation; CD27 signaling pathway; extrinsic apoptotic signaling pathway; T cell activation; T cell mediated immunity; positive regulation of T cell proliferation; immune response; lymphocyte proliferation; T cell proliferation; tumor necrosis factor-mediated signaling pathway
Cellular component: extracellular exosome; plasma membrane; membrane
Genetic constraint (gnomAD): Loss-of-function variants: 9 observed, 12.55 expected, observed/expected ratio (o/e) 0.72, 90% interval 0.43 to 1.25. The upper end of that interval is the gene's LOEUF score, 1.25, which puts it in group 5 of 6, group 1 being the genes least tolerant of losing a copy. Missense variants: 235 observed, 270.85 expected, observed/expected ratio (o/e) 0.87, 90% interval 0.78 to 0.97. Synonymous variants: 108 observed, 118.71 expected, observed/expected ratio (o/e) 0.91, 90% interval 0.78 to 1.07.
Gene-disease validity (ClinGen):
ClinGen rates the evidence that CD70 causes each of these diseases.
severe combined immunodeficiency due to CD70 deficiency (autosomal recessive): Definitive.
Homologues: Orthologues: macaque CD70 (93% identical), chimpanzee CD70 (83% identical), dog CD70 (69% identical), pig CD70 (66% identical), mouse Cd70 (57% identical), guinea pig Cd70 (56% identical), rat Cd70 (55% identical).
Diseases named in the same sentence as CD70 in open-access papers:
CD70 is named in the same sentence as 176 diseases in open-access papers, as found by Europe PMC text mining. Sharing a sentence is not in itself a finding about the gene and the disease. The quoted sentences say what the papers report.
glioma (48 papers, 2006 to 2026). A benign or malignant brain and spinal cord tumor that arises from glial cells (astrocytes, oligodendrocytes, ependymal cells). "CD70 is a receptor that is overexpressed in glial tumor cells associated with poor survival, which binds CD27." (PMID 37830595, 2023). "High-grade gliomas present robust expression of CD70 mainly in the GBM with the IDH-wild type variants, including epithelioid glioblastoma and gliosarcoma." (PMID 32429463, 2020). "High CD70 expression was associated with poor prognosis in glioma patients." (PMID 39227950, 2024). "In vivo studies on murine glioma models indicate that CD70-targeted therapies can cause tumor regression, but contrasting evidence suggests that the CD27 pathway might also suppress T lymphocytes." (PMID 38342925, 2024). "High expression of CD70 is an independent prognostic risk factor for glioma." (PMID 36387186, 2022). "Human renal clear cell adenocarcinoma 786-0 cells and glioma U251 cells were selected as target cell lines due to their high expression of CD70." (PMID 40165944, 2025). "HOXC6, WT1, CD70, and OTP expression was elevated in glioma tissues from high-risk score patients carrying wild-type TERTp." (PMID 38499392, 2024). "HOXC6, WT1, CD70, and OTP expression was upregulated in glioma tissues from patients with high-risk scores." (PMID 38499392, 2024). "CAR T cells targeting CD70, a novel target in gliomas, have also been investigated in immunocompetent models." (PMID 39335157, 2024). "We further investigated the correlation between CD70 expression and Treg infiltration in glioma and found that CD70 expression was significantly positively correlated with Treg infiltration." (PMID 39227950, 2024). "To obtain insight into the function of CD70 in glioma, we analyzed the relationship between CD70 expression and patient prognosis." (PMID 39227950, 2024). "Based on multivariate Cox regression analysis, the immune signature created using HOXC6, WT1, CD70, and OTP represented an independent prognostic factor for glioma patients with TERTp mutations." (PMID 38499392, 2024). "In vitro cellular experiments demonstrated that 70R CAR-T cells exhibited markedly increased cytotoxic activity against CD70-positive glioma cells." (PMID 39506843, 2024). "CD70 expression in glioma cells can trigger T-cell apoptosis and tumor growth inhibition, possibly due to NK cell activity or differences in the apoptosis-regulating Siva pathway." (PMID 38342925, 2024). "TGFB1, VEGFA, ARG1, and IL10 are secreted immunosuppressive factors in glioma, while CD70 is a glioma cell-surface immunosuppressive factor." (PMID 37891828, 2023). "This further broadens the utility of CD70/CD27 axis blockade, and a CD70‐specific CAR T cell strategy has also recently been tested for gliomas." (PMID 36471481, 2022). "In contrast to normal tissue, CD70 is expressed in brain tumor cells, especially gliomas and meningiomas." (PMID 35236310, 2022). "TGFB1, VEGFA, ARG1, FGL2 and IL10 are secreted immunosuppressive factors in glioma, while CD95L and CD70 are glioma cell‐surface immunosuppressive factors." (PMID 33611848, 2021). "Recent reports provided proof that CD70 expression was undetected in normal tissues from diverse organs; however, it was highly expressed in glioma tissues, indicating that CD70 expression is typically confined to tumors." (PMID 32429463, 2020). "For detecting the expression of B7-H3 and CD70, multiple tumor microarrays including kidney, breast, esophageal, liver and colon cancer as well as melanoma, glioma and normal tissues specimen were stained by the method of IHC." (PMID 32685008, 2020). "In the glioma microenvironment, FASL (CD95L), programmed cell death ligand 1/2 (PD-L1/2), galectin-1, galectin-9, HVEM, B7-H4 (B7x), and CD70/gangliosides expressed on glioma cells act as inhibitory ICMs." (PMID 32707672, 2020).
glioma (continued). "To determine the molecular mechanism by which POSTN regulates CD70 expression in glioma, we performed chromatin immunoprecipitation enrichment analysis (ChEA) of RNA-seq data from HMC3 cells to identify transcription factors that potentially mediate transcriptional changes in microglia." (PMID 39227950, 2024). "However, MAPKAPK2 is positively correlated with a series of immune regulators such as CD274, CD276, PDCD1, and CD70, which probably affect the tumor killing effect of the infiltrated immune cells in glioma tissue." (PMID 38322416, 2024). "HOXC6, WT1, CD70, and OTP were highly expressed in high-risk vs. low-risk glioma samples." (PMID 38499392, 2024). "Moreover, the high/low radiomics scores were highly correlated with the known glioma‐related genes, including CD70, CD27, and PDCD1." (PMID 39030882, 2024). "Moreover, on targeting CD70 expressing glioma cells using CAR-T cells, tumor regression was observed in glioma mouse models." (PMID 37046685, 2023). "In the cancer-immunity cycle, we found genes that inhibit the cycle, including the glioma-secreted and cell-surface immunosuppressive factors, TGFB1, VEGFA, ARG1, IL10, and CD70, they were highly expressed in the high-risk group and were positively correlated with the risk score." (PMID 37891828, 2023). "Furthermore, we excluded the use of the CAR-T target of gliomas: CD70, which can consistently activate T cells and lead to T cell dysfunction." (PMID 36428765, 2022). "Of note, B7-H3 CD70 co-expression has also been reported in glioma." (PMID 36303101, 2022). "Recent evidence revealed that CAR T cells targeting CD70 could inhibit the growth of glioma, head and neck squamous cell carcinoma, and multiple solid tumors as well as hematologic malignancies in vitro and in vivo." (PMID 35145909, 2021). "For example, CD70, which is highly expressed in glioma, can promote macrophage infiltration into a tumor, and JAK1 was shown to be positively correlated with the infiltration of various immune cells in breast cancer, such as CD8+ T cells and dendritic cells, etc.." (PMID 34098960, 2021). "Subsequent studies have described overexpression of CD70 protein in mantle cell lymphoma samples; on chronic lymphocytic leukaemia B cells; and in the tumour cells of thymic carcinomas, undifferentiated nasopharyngeal carcinomas, gliomas and meningiomas." (PMID 16892042, 2006). "Moreover, the interactions of CD70, HLA-E, HVEM, FALSG, and LGALS1 expressed on the glioma cell surface and their corresponding receptors have been reported to cause T cell dysfunction, thereby enabling glioma cells to evade immune-mediated killing." (PMID 37056564, 2023). "Finally, it was demonstrated that radiotherapy, similar to what was seen with chemotherapy, could increase membrane CD70 expression in glioma, leukemia and lymphoma." (PMID 34991665, 2022). "No negative adverse effects were detected in the syngeneic or xenograft models treated, establishing CD70 CAR safety in vivo and their potential for treating patients with refractory gliomas." (PMID 39335157, 2024). "ELF4 is elevated in high grade gliomas, particularly in glioma and neuronal stem cell markers, including CD44, CD36, CD15, CD70, S100A4, and ALDH1A3." (PMID 38539424, 2024). "In conclusion, an immune signature based on HOXC6, WT1, CD70, and OTP expression was shown to serve as an independent and specific prognostic indicator for patients with TERTp- mutant gliomas." (PMID 38499392, 2024). "Human- and murine-derived CD70 CAR-T cells demonstrated tumor regression in in vitro studies, human xenograft models, and syngeneic in situ glioma models." (PMID 39506843, 2024). "Our study found that several immune checkpoints (BTLA, CD200R1, PD-L1, B7-H3, CD70, CTLA4, IDO1, and PD1) in patients with CDC42 high expression glioma were upregulated compared to the CDC42 low expression group." (PMID 37476838, 2023).
glioma (continued). "ALKBH5 expression showed positive association with ICP receptors such as TNFRSF14, CD40, CD96 and CD200R1, and ICP ligands such as PDCD1LG2, CD70, TNFSF14, ICOSLG and CD274 in glioma tissues." (PMID 35444654, 2022). "Chimeric antigen receptors (CARs) also paved the way for a novel approach to cancer therapy; several CARs have been established against gliomas by targeting IL13Rα2, EGFRvIII, HER2, and CD70." (PMID 36146527, 2022). "CAR-T cell therapy paved the way for a novel approach in cancer therapy; several CARs have been established against gliomas by targeting IL13Rα2, EGFRvIII, HER2, and CD70." (PMID 36146527, 2022). "Recently, new targets of CAR T cells in glioma: podoplanin (PDPN), a member of type I transmembrane glycoproteins, as well as CD70, one of the tumor necrosis factor receptors have been recognized." (PMID 33673696, 2021). "Furthermore, we also examined the expression of several other key genes associated with immune regulation in different groups, including KLRB1, CD70, and FASLG, which have been shown to play key roles in glioma immune evasion." (PMID 38971948, 2024). "Rad_score was positively correlated with glioma‐related genes, such as PDCD1, CD27, and CD70." (PMID 39030882, 2024). "CD70 CAR-T cells could preferentially retract CD70 in xenograft mice, which confirms a new CAR target for glioma immunotherapy." (PMID 36146527, 2022). "To investigate whether CYB561D2-activated STAT3 induces the expression of immunosuppressive genes in gliomas, we measured protein expression of FASLG, TGF-β2, CD70, PD-L1, PD-L2, CCL2 and TDO2 in U251 and U87 transfected with CYB561D2 plasmid for 48 h." (PMID 34372858, 2021). "We observed correlations between high CD70 mRNA expression and poorer prognosis in ovarian, lung, gastric and breast cancer patient but not in glioma cases." (PMID 29721188, 2018). "Therefore, we hypothesized that high ALKBH5 expression altered the immune microenvironment in the glioma tissues by modulating the expression levels of ICP receptors and ligands such as TNFRSF14, CD40, CD96, PDCD1LG2, CD70 and TNFSF14." (PMID 35444654, 2022). "A discussion of the pathophysiological role of cytokines in glioma is reviewed elsewhere, and the role of several of the specific genes demonstrating enrichment of the cytokine-cytokine receptor interaction KEGG pathway has previously been discussed (CD70, IL-12β, IL-1β)." (PMID 31475119, 2019). "Additionally, CD70 overexpression was detected in a multidrug-resistant colonic cell line (SW620-MDR), and as an inducible gene in TNF-alpha-stimulated human bronchial–epithelial cell line BEAS-2B, and irradiated glioma cell lines." (PMID 16892042, 2006). "Focusing on the TERTp-mutant glioma subtype, we developed an immune-related gene signature including HOXC6, WT1, CD70, and OTP that showed significant prognostic value for TERTp-mutant gliomas, but not for TERTp wild-type gliomas, in two TCGA cohorts." (PMID 38499392, 2024).
melanoma (47 papers, 2004 to 2025). A malignant, usually aggressive tumor composed of atypical, neoplastic melanocytes. "TriMixDC-MEL, autologous monocyte-derived mRNA co-electroporated dendritic cells with mRNA encoding CD40L, CD70, and caTLR4, was administered i.v. to 21 late-stage melanoma patients." (PMID 36830845, 2023). "Altogether these results demonstrated that RhoA and MAPK pathways are associated in positive and transcriptional regulation of CD70 expression in melanoma." (PMID 26828592, 2016). "This study also demonstrated that melanoma-expressed CD70 is implicated in tumor migration, invasion and metastasis." (PMID 26828592, 2016). "Ectopic, melanoma-expressed CD70 is implicated in melanoma invasiveness, with monomeric CD70 diminishing metastatic potential in vitro and in vivo, whereas the trimeric form, as in mAb-mediated cross-linking, restores melanoma-cell migratory capacity." (PMID 37345056, 2023). "Our current study revealed that an interaction between CD27 and CD70 in the TME of melanoma patients, with CD70 primarily expressed by stromal cells in this context." (PMID 40148586, 2025). "For instance, the co-expression of CD40L with GM-CSF in bystander cells and with toll-like receptor 4 (TLR4)/CD70 or TLR4/CD70/tumor antigen in autologous DCs was employed for the treatment of advanced lung adenocarcinoma and advanced melanoma." (PMID 39120299, 2024). "To verify the pro-tumor effect of CD70 in melanoma, we performed CD70-KO in a murine melanoma cell line: B16-F10, and orthotopically injected CD70-NC and CD70-KO B16-F10 cells in C57BL/6J mice." (PMID 37024479, 2023). "CD70-KO led to significant melanoma shrink, but we also observed a tumor-specific response to CD70-KO, possibly due to the mouse-specific TME." (PMID 37024479, 2023). "It was reported in melanoma that CD70 expression regulates invasion and metastasis intrinsically, rather than through the TME." (PMID 34991665, 2022). "In melanoma, CD70 expression led to MAPK activation and RhoE overexpression, thereby promoting tumor migration." (PMID 34991665, 2022). "While the monomeric form of CD70 limited the metastatic and migratory ability of melanoma cells, the trimeric form of CD70 enhanced cell migration and invasiveness." (PMID 34991665, 2022). "A DC-based mRNA vaccine encoding CD40Ligand, CD70, and TLR4 (TriMixDC), and transfected with melanoma associated genes (MAGE, Tyrosinase, gp100-TriMix-MEL) was evaluated in a cohort of advanced melanoma patients." (PMID 36016150, 2022). "As expected, two models of human lung cancer and melanoma treated with TanCAR-T cells showed a more significant decrease in tumor burden, comparable to NT, CD70 CAR2 and B7-H3 CAR-T cells treated groups." (PMID 32685008, 2020). "Recently, using patients’ biopsies and human melanoma cell lines, we investigated the ectopic expression of CD70 in melanoma tumor cells." (PMID 26828592, 2016). "We have recently described its expression in a part of tumor cells from the vast majority of melanoma biopsies and human melanoma cell lines, and found that CD70 expression decreased over time as the disease progressed." (PMID 26828592, 2016). "Our results showed that RhoA and MAPK pathway cross-talk to positively regulate melanoma-expressed CD70." (PMID 26828592, 2016). "Altogether, these data show that RhoA positively controls transcriptional levels of ectopic CD70 in human melanoma cells." (PMID 26828592, 2016). "In melanoma cell lines the monomeric form of CD70 is associated with reduced migration, invasion and metastasis capacities, whereas the active trimeric form of CD70 induces the activation of a signaling pathway, which favors melanoma invasiveness." (PMID 26828592, 2016). "In vitro treatment of the three CD70+ melanoma cell lines with PLX-4032 induced membrane and global CD70 decrease." (PMID 26828592, 2016). "Altogether our experiments show that the expression of CD70 in melanoma cells is under the control of RhoA and the MAPK pathway." (PMID 26828592, 2016).